LATS1 (large tumor suppressor kinase 1)
Diseases named in the same sentence as LATS1 in open-access papers (continued):
Sharing a sentence is not in itself a finding about the gene and the disease.
pancreatic cancer (10 papers, 2016 to 2025). "The lncRNA MALAT, which is highly expressed in pancreatic cancer tissues, also targets LATS1, and knockdown of MALAT also induces apoptosis in pancreatic cancer cells." (PMID 33582842, 2021). "The level of ITCH and LATS1 expression were determined in 30 paired pancreatic cancer samples and matched adjacent, histologically normal tissues by qRT-PCR, and normalized to TBP expression (internal control)." (PMID 26621835, 2016). "Therefore, we examined the effects of PR55α on the core members of this pathway (MST1/2, MOB1, and LATS1/2) in pancreatic cancer cells using Dox-inducible shRNAs." (PMID 31659153, 2019). "In pancreatic cancer, tumor cell-intrinsic PD-1 interacts with MOB1 and decreases MOB1 phosphorylation, thereby suppressing the phosphorylation of LATS1 and inactivating LATS1, which inhibits YAP phosphorylation and accumulates YAP protein." (PMID 34326692, 2021). "We investigated the role of LATS1/2 in the activation of YAP by PR55α in CD18/HPAF and AsPC-1 pancreatic cancer cells." (PMID 31659153, 2019). "In the present study, we analyzed LATS1 and ITCH expression in pancreatic tumor tissue specimens compared to normal pancreatic tissue specimens and correlated the expression levels to overall survival and percent disease progression." (PMID 26621835, 2016). "Indeed, Gαi3 shRNA or KO led to enhanced activation of PKA and the Hippo pathway kinase LATS1/2, coupled with the inactivation of YAP/TAZ in primary pancreatic cancer cells." (PMID 39349432, 2024). "Moreover, increased activation of PKA and Hippo kinase LATS1/2, as well as the inactivation of YAP/TAZ, were significantly increased in Gαi3-depleted pancreatic cancer xenograft tissues." (PMID 39349432, 2024). "Our results suggest that MST1/2 and LATS1/2 protein did not change markedly based on modulation of GPRC5A expression, which indicated that the regulation of YAP1 by GPRC5A is independent of LATS1/2 kinase in pancreatic cancer cells." (PMID 36735162, 2023). "We also analyzed the effect of LATS1/2 on YAP-S127 phosphorylation in the presence/absence of PR55α-knockdown in pancreatic cancer cells." (PMID 31659153, 2019). "However, levels of ITCH expression, its correlation to LATS1 levels and function, and its regulation has not yet been established in the context of pancreatic cancer." (PMID 26621835, 2016). "We next determined the steady state LATS1 and ITCH protein expression levels in the non-metastatic pancreatic cancer cell line, BxPC-3 and the metastatic pancreatic cancer cell line, PANC-1." (PMID 26621835, 2016). "While YAP signaling clearly supported the proliferation of RNF43-mutant pancreatic cancer, the sgRNAs targeting YAP suppressors SAV1 or LATS1 were not further enriched by ETC-159 treatment, suggesting that YAP activation could not bypass Wnt dependency in RNF43-mutant pancreatic cancer." (PMID 35536676, 2022). "However, these factors are not related to the Wnt-independency phenotype in RNF43-mutant pancreatic cancer, since sgRNAs targeting KDM6A or negative regulators of GLI2 or YAP1, i.e., PTCH1, LATS1, and SAV1, were not enriched in ETC-159 versus vehicle-treated tumors in our initial CRISPR screens." (PMID 35536676, 2022).
astrocytoma (9 papers, 2012 to 2023). "LATS1/2 promoter hypermethylation was also found in U251 and SHS-44 GBM cell lines and was associated with correspondingly decreased mRNA expression in astrocytoma samples." (PMID 33477668, 2021). "Gene mutations in key protein domains and methylation in promoter region frequently occur in human stomach adenocarcinoma and astrocytoma tissues and eradicates normal function of LATS1 leading to the production of neoplasm." (PMID 26921249, 2016). "In a series of 88 tumors, the percentage of tumors with downregulation of LATS1 and LATS2 due to promoter hypermethylation increased significantly from 48%/52% in grade 2 astrocytomas to 65%/70% in grade 3 astrocytomas and to 73%/82% in grade 4 glioblastomas." (PMID 37626776, 2023). "Involvement of the inactivated hippo pathway due to decreased expression of MST1/2 or LATS1/2 or even due to the overactivation of YAP1 and TAZ has been confirmed in various tumor types, such as colorectal and prostate cancer and even in astrocytomas and glioblastomas." (PMID 37626776, 2023). "In addition, promoter hypermethylation mediates decreased expression of LATS1 and LATS2 in human astrocytoma." (PMID 26942001, 2016).
renal cell carcinoma (9 papers, 2019 to 2025). "Interestingly, a Gly553Glu mutation of LATS1 was found in patients with renal cell carcinoma." (PMID 31486770, 2019). "In renal cell carcinoma, tazemetostat treatment reduces H3K27me3 level and increases LATS1 expression, thereby exerting beneficial function." (PMID 40478495, 2025). "DGT induces YAP retention in the renal cell carcinoma cell cytoplasm by activating LATS1/2 protein phosphorylation and blocks YAP‐TEAD1 interaction to down‐regulate YAP and its target genes (associated with the Hippo pathway)." (PMID 39155844, 2024). "Furthermore, EZH2 inhibition exerts an antineoplastic effect against renal cell carcinoma through inactivation of large tumor suppressor 1 (LATS1)." (PMID 40243914, 2025). "Recent studies have demonstrated that the deletion of Lats1/2 in adult kidney epithelium leads to the development of renal cell carcinoma (RCC), suggesting that LATS1 functions as a tumor suppressor that negatively regulates tumor progression." (PMID 40521202, 2025). "Given that EZH2 plays a crucial role in renal cell carcinoma by directly binding to the LATS1 promoter to inhibit its expression and promote tumor growth, we hypothesized that the protective effects of ZLD1039 in UUO-induced renal fibrosis might be mediated by LATS1 expression and activation." (PMID 40478495, 2025).
sarcoma (9 papers, 2014 to 2023). A usually aggressive malignant neoplasm of the soft tissue or bone. "Published data indicated that transgenic mice with mutations in members of the Hippo pathway, including LATS1/2, develop sarcomas." (PMID 34440844, 2021). "Approximately 49% of sarcomas (73/148) demonstrate loss of MST1, 31% of sarcomas (46/148) demonstrate loss of MST2, 23% of sarcomas (34/148) demonstrate loss of LATS1 expression, and 29% of sarcomas (45/153) demonstrate loss of LATS2." (PMID 30167083, 2018). "Studies show that promoter methylation of Lats1 and Lats2 is common in schwannomas (17% and 30%, respectively), while promoter methylation of Mst1 and Mst2 has been detected in 37% and 17% of sarcomas, respectively." (PMID 32960816, 2020). "The Itch E3 ubiquitin protein ligase has already been implicated in regulation of LATS1, we also identify that MST2's expression is negatively regulated by a ubiquitin ligase in several sarcoma cell lines." (PMID 30167083, 2018). "Evaluation of 259 sarcomas in The Cancer Genome Atlas demonstrated a mutation rate ranging from 0% for MST2 and LATS1 to 0.8% for LATS2." (PMID 30167083, 2018). "By immunohistochemistry, TAZ/YAP activated clinical sarcoma samples demonstrated loss of MST1 (47%), MST2 (26%), LATS1 (19%), and LATS2 (27%)." (PMID 30167083, 2018). "Approximately 8% of sarcoma cell lines demonstrated loss of expression of LATS1 at the RNA level, while no cell lines demonstrated loss of expression of LATS2 at the RNA level." (PMID 30167083, 2018). "Loss of expression of LATS1 and LATS2 was noted in 8% (9/113) of sarcomas." (PMID 30167083, 2018). "Within these TAZ/YAP activated sarcomas, 47% (54/114) demonstrated loss of MST1 expression, 26% (30/117) demonstrated loss of MST2 expression, 19% (22/113) of the sarcomas demonstrated loss of LATS1 expression, and 27% (32/117) of the sarcomas demonstrated loss of LATS2 expression." (PMID 30167083, 2018). "We thus assessed the functional role of LATS1 in rapamycin-induced autophagy in standard cellular models, such as U2OS sarcoma cells." (PMID 31848340, 2019). "Loss of expression of the Hippo kinases was identified in clinical sarcoma samples demonstrating activated TAZ and YAP at a relatively high level, ranging from 19% (LATS1) to 47% (MST1)." (PMID 30167083, 2018).
glioblastoma (8 papers, 2016 to 2023). The most malignant astrocytic tumor (WHO grade IV). "However, IKKε was also reported to induce the ubiquitination and proteasomal degradation of LATS1/2 in glioblastoma multiforme cell lines, causing YAP activation." (PMID 31225446, 2017). "The growth, migration, and invasion of glioblastoma cells are inhibited by the overexpression of LATS1, which regulates cell cycle progression." (PMID 37423952, 2023). "In INF2-depleted glioblastoma cells, CaAR is disrupted and Ca2+-induced phosphorylation of Lats1 and YAP is compromised, suggesting that CaAR is important for the Hippo pathway activation by Ca2+." (PMID 34268313, 2021). "A selective inhibitor of IKKε, amlexanox, reverses the inhibition of IKKε on LATS1/2 and thus declines glioblastoma cell migration and invasion and glioblastoma growth in xenograft mouse model." (PMID 31225446, 2017).
prostate carcinoma (7 papers, 2013 to 2025). A carcinoma that arises from epithelial cells of the prostate gland. "Genes encoding mediators of cytoplasmic retention of YAP such as 14‐3‐3 and Lats1/2 were downregulated by flow in positive responding breast cells and upregulated in prostate cancer cells." (PMID 35520391, 2022). "In recent studies, miR-103a-3p has been reported to promote migration, invasion, and apoptosis of thyroid cancer cells by downregulating LATS1 via Hippo signaling, while in prostate cancer, miR-103a-3p has been shown to suppress the proliferation and invasion by targeting D52." (PMID 34307670, 2021). "An in vitro study showed diosgenins’ anti-tumor and apoptotic effects in PC-3 prostate cancer via downregulation of NEDD4 and modulation of pAkt, P73 and LATS1." (PMID 41346617, 2025). "Further examining the correlation between levels of LATS1 and WWP1 using clinical breast and prostate cancer may provide further in vivo data regarding how dysregulation of these two proteins are involved in the development of human cancers." (PMID 23573293, 2013).
lung adenocarcinoma (6 papers, 2015 to 2023). A carcinoma that arises from the lung and is characterized by the presence of malignant glandular epithelial cells. "Loss of LATS1/2 or other Hippo pathway alterations could confer resistance to erlotinib in HNSCC cells with EGFR overexpression or lung adenocarcinoma cells harboring EGFR mutations." (PMID 34725466, 2021). "To examine the importance of YAP/TAZ activation under EGFR in HNSCC and lung adenocarcinoma cells, we genome edited the LATS1 and LATS2 genes to activate YAP/TAZ in both cells harboring EGFR alterations." (PMID 34725466, 2021). "Consistent with this hypothesis, mutations in LATS1 were also significantly enriched among lung adenocarcinomas lacking oncogenic driver mutations in the RTK–RAS–ERK pathway." (PMID 32641858, 2020). "However, it is unclear concerning the clinical significance of LATS1 and the regulatory mechanisms of 17-Allylamino-17- demethoxygeldanamycin (17-AAG) in lung adenocarcinoma (LAC)." (PMID 25712415, 2015).
osteosarcoma (6 papers, 2015 to 2025). A usually aggressive malignant bone-forming mesenchymal neoplasm, predominantly affecting adolescents and young adults. "In osteosarcoma cells, MIR100HG promotes proliferation by interacting with the EZH2 protein of the polycomb repressor complex-2, causing repression of LATS1/2, mediators of Hippo signaling." (PMID 33941855, 2021). "To further investigate the role of the Hippo/YAP pathway in osteosarcoma chemoresistance, we evaluated LATS1/2 total protein level and Ser127 phosphorylation of YAP in osteosarcoma cells." (PMID 27206784, 2016). "We observed that LATS1/2 total protein decreased in osteosarcoma cells treated with methotrexate or doxorubicin." (PMID 27206784, 2016). "High MIR100HG expression was determined as a poor prognosis factor in osteosarcoma patients, and its upregulation was found to suppress Hippo signaling activity via the epigenetic silencing of Large tumor suppressor kinases 1 and 2 (LATS1/2)." (PMID 40862737, 2025). "In the present study, we showed that, in osteosarcoma cells, methotrexate and doxorubicin activated YAP, promoting its nuclear translocation by accelerating MST1 protein degradation and decreasing LATS1/2 protein level." (PMID 27206784, 2016). "Furthermore, downregulation of DEPDC1 activated the Hippo signaling pathway, leading to the overexpression of p-LATS1 and p-YAP, which in turn inhibited YAP and suppressed the proliferation of osteosarcoma cells." (PMID 40600015, 2025).
schwannoma (6 papers, 2016 to 2026). A benign, usually encapsulated slow growing tumor composed of Schwann cells. "Firstly, complete loss of both Lats1 and Lats2 in the Hoxb7+ lineage resulted in multiple schwannoma formation." (PMID 32960816, 2020). "Our results show that loss of heterozygosity of the residual WT Lats1 or Lats2 allele in H7;Lats1/2mut3 mice is required for schwannoma development." (PMID 32960816, 2020). "Accordingly, we and others must ablate 4 alleles of Lats1/2 in order to completely block the Hippo pathway for schwannoma induction, making human sporadic loss of function mutations unlikely." (PMID 32960816, 2020). "Lats1 or Lats2 loss of heterozygosity in H7;Lats1/2mut3 mice is required for schwannoma development." (PMID 32960816, 2020). "Furthermore, whole-exome sequencing of inherited and sporadic schwannoma reported LATS1 mutations, suggesting that Hippo signaling could play a role in both types of schwannoma." (PMID 31450674, 2019). "Other recurrently altered genes reported in schwannomas include LATS1, LATS2, ARID1A, ARID1B and DDR1." (PMID 41300852, 2025). "Previous studies have shown that KO of Lats1/2 gene with a broad Schwann cell Cre, such as Dhh-Cre, results in direct malignant transformation and bypasses the benign schwannoma stage." (PMID 32960816, 2020). "If the Hippo pathway is crucial for schwannoma development, inactivation of Lats1/2 should result in YAP/TAZ dephosphorylation and nuclear localization." (PMID 32960816, 2020). "Consistent with this, in vitro treatment of a mouse schwannoma cell line (FC-1801), with the first in class neddylation inhibitor pevonedistat, reduced LATS1/2 ubiquitination and increased YAP phosphorylation." (PMID 32629964, 2020). "Dysregulated Hippo-Lats1/2-YAP/TAZ pathway leads to schwannoma development." (PMID 32960816, 2020). "Only 2% and 1% of human schwannomas carry Lats1 and Lats2 mutations, respectively, and no Mst1/2 mutation has been reported in human cancer." (PMID 32960816, 2020). "Targeted sequencing of LATS1 and LATS2 in sporadic schwannoma revealed mutations in 1% and 2% of cases, respectively, suggesting that their mutation may be rare." (PMID 31450674, 2019). "However, NF2 loss in the Schwann cell lineage could also lead to schwannoma development, and although the likelihood is very low, it is still possible that schwannomagenesis may result from NF2 loss/downregulation as a result of Lats1/2 loss." (PMID 32960816, 2020). "While H7;Lats1/2mut3;YAP/TAZ mut4 mice showed significantly reduced tumor burden, they still developed schwannomas." (PMID 32960816, 2020). "All of the H7;Lats1/2mut3;YAP/TAZmut mice were viable, fertile, and normal in size, with no gross behavioral or physical abnormalities except for multiple schwannomas with 100% penetrance." (PMID 32960816, 2020).
non-small cell lung carcinoma (5 papers, 2020 to 2022). A group of at least three distinct histological types of lung cancer, including non-small cell squamous cell carcinoma, adenocarcinoma, and large cell carcinoma. "A recent study concluded that lncRNA GHET1 promotes cell invasion and proliferation in non-small cell lung cancer by regulating the LATS1/YAP signaling pathway, the findings of which were consistent with our study." (PMID 34401209, 2021).
oral squamous cell carcinoma (5 papers, 2019 to 2025). "The downregulation of LATS1/2 by promoter methylation has been linked to the development of oral squamous cell carcinoma." (PMID 34401209, 2021). "In contrast, another study observed that LATS1/2 expression was elevated in oral squamous cell carcinoma." (PMID 40699764, 2025). "Here, we found that LATS1/2, the core Hippo pathway-kinases, were highly expressed in the oral squamous cell carcinoma line SAS, which exhibits high capacity of CSCs, and that depletion of these kinases prevented SAS cells from forming spheres under serum-free conditions." (PMID 30800215, 2019).
ovarian tumors (5 papers, 2012 to 2020). "Loss of heterozygosity in the LATS1 chromosomal region was reported in ovarian tumors, breast tumors and adenoid cystic carcinoma." (PMID 25628642, 2014).
renal carcinoma (5 papers, 2018 to 2025). A carcinoma arising from the epithelium of the renal parenchyma or the renal pelvis. "Upstream regulators of the Hippo pathway, such as NF2 and LATS1/2, are frequently mutated or downregulated in renal cancer tissues, resulting in pathway inactivation." (PMID 39092291, 2024). "This study collectively demonstrates that SPOP promotes the ubiquitination and degradation of LATS1, thereby enhancing renal cancer cell invasion." (PMID 40771930, 2025). "Activated LATS1 possesses the ability to degrade YAP by phosphorylating YAP; moreover, the demethylation of LATS1 can repress cell proliferation and promote cell apoptosis in renal cancer by decreasing the level of YAP." (PMID 34401209, 2021). "In an immunohistochemical study lower LATS1 protein expression was found in renal cancer tissue and it correlated with the clinical stage and pathological grade of ccRCC." (PMID 29850494, 2018). "SPOP has been identified as a novel E3 ligase for LATS1 in ccRCC cells, with the E3 ubiquitin ligase Cullin3/SPOP mediating the stability of LATS1 through polyubiquitination, leading to its degradation in a degron-dependent manner in renal carcinoma." (PMID 40771930, 2025). "Interventions targeting pivotal components of this pathway, including LATS1/2 and YAP/TAZ, may serve as effective approaches for the future treatment of renal cancer." (PMID 39092291, 2024).